NOS1 (nitric oxide synthase 1)
Diseases named in the same sentence as NOS1 in open-access papers (continued):
Sharing a sentence is not in itself a finding about the gene and the disease.
melanoma (continued). "NOS1 overexpression significantly inhibited IFNB1 and IRF7 transcription in A375 melanoma cells in response to Poly(I:C) stimulation, and this inhibition was reversed by NOS1-knockout." (PMID 41535256, 2026). "NOS1 reduces the recruitment of STAT1-mediated HDAC2 to ISG promoters and promotes lung metastasis of melanoma through the S-nitrosylation of HDAC4-C16/C229." (PMID 38877096, 2024). "To generate NOS1-deleted melanoma cell lines, we constructed a CRISPR/Cas9 plasmid with a gRNAs targeting the exon six of NOS1 gene and transfected into A375 cells." (PMID 35538490, 2022). "To confirm the results, we also performed a similar study in mouse melanoma cells B16F10, and RT-PCR results showed that NOS1 inhibited the induction of ISGs in both in vivo and in vitro experiments." (PMID 31805977, 2019). "In this study, we found that a small amount of IRF7 in resting tumor cells can be modified by NOS1-mediated S-nitrosylation, thereby inhibiting IRF7-mediated transcription of IFNB1, resulting in impaired activation of the type I IFN signaling in melanoma cells." (PMID 41535256, 2026). "In this study, we investigated the role of NOS1 expression in regulating IRF7 function by S-nitrosylation regulation, and found that NOS1 induces IRF7 S-nitrosylation, which inhibits the activation of type I IFNs signal in melanoma, leading to the formation of an immunosuppressive microenvironment." (PMID 41535256, 2026). "Clinically, NOS1 expression significantly reduced the infiltration of CD8+ T cells in the tumor microenvironment and was negatively correlated with the survival prognosis of cold melanoma patients." (PMID 41535256, 2026). "To validate the role of NOS1 in immune escape, we established lung metastasis of melanoma cells with or without NOS1 expression (NOS1-KO B16 and WT B16) in immune competent C57BL/6 mouse." (PMID 35538490, 2022). "Furthermore, NOS1 was closely related to dysfunctional IFN signaling, and an inhibitor of NOS1 resulted in reduced proliferation of melanoma cells." (PMID 31805977, 2019). "However, the immune regulatory role and related mechanisms of NOS1, as well as its impacts on immune therapies such as immune checkpoint blockade (ICB) in melanoma, remain unclear." (PMID 41535256, 2026). "However, the molecular function of NOS1 in the type I IFN response and immune escape of melanoma is still unknown." (PMID 35538490, 2022). "Of 471 melanoma clinical samples, NOS1 expressed low level in most samples and found no different among four clinical stages and could not predicate the survival prognosis of patients (data not shown)." (PMID 35538490, 2022). "In the TCGA data, the proportion of tumor-infiltrating CD8+ T cells was significantly reduced in the high NOS1 expression subgroup only in the melanoma group with low CD45 expression, but not in the CD45 high melanoma group." (PMID 41535256, 2026). "Our data from patient biopsies, showed that there were no significant alterations in the NOS1 and NOS3 expression levels during melanoma progression." (PMID 35326089, 2022).
Parkinson disease (22 papers, 2010 to 2025). A progressive degenerative disorder of the central nervous system characterized by loss of dopamine producing neurons in the substantia nigra and the presence of Lewy bodies in the substantia nigra and locus coeruleus. "Recently, the polymorphisms of several genes, such as CYP1A1, CYP1A2, ABCB1, PON1, PON2, and NOS1, were considered as the candidate risk factors for Parkinson's disease." (PMID 27749554, 2016). "Mutation recorded in exon 29 of the NOS1 gene in our study of Parkinson's disease (PD) patients." (PMID 37849584, 2023). "Therefore, it is possible that Parkinson's disease is susceptive to the polymorphisms of NOS1." (PMID 27749554, 2016). "In animal models, inhibition of nNOS prevents MPTP-induced Parkinsonism in both baboons and mice, and MPTP-induced neuronal damage is diminished in mice lacking either the NOS1 or the NOS2A gene." (PMID 26383258, 2016).
Hyperglycemia (20 papers, 2010 to 2025). An increased concentration of glucose in the blood. "Knock-out of NOS1 in leptin receptor- and NOS1-expressing hypothalamic neurons results in hyperphagic obesity, decreased energy expenditure, and hyperglycemia in mice." (PMID 28396702, 2017). "Furthermore, activation of NOS1 neurons (VMHNOS1) in the VMH elicits hyperglycaemia, indicating that a large majority of VMHNOS1 appears to be GI neurons, although NOS1 neurons are a subset of VMHSF1 neurons." (PMID 35619170, 2022).
atherosclerosis (19 papers, 2012 to 2025). A disease characterized by the build-up of fatty material and calcium deposition in the arterial wall resulting in partial or complete occlusion of the arterial lumen. "The nitric oxide synthase 1 (NOS1) enzyme can affect the synthesis of NO (nitric oxide), which is involved in the pathogenesis of atherosclerosis." (PMID 26114387, 2015).
Obesity (19 papers, 2013 to 2025). Accumulation of substantial excess body fat. "Conversely, in the later phase of obesity, when hippocampal nNOS protein levels are high, Nos1 mRNA expression is low." (PMID 36091357, 2022). "We previously reported that hippocampal Nos1 mRNA expression is low in the initial phase of HFD-induced obesity, prior to the upregulation of nNOS protein." (PMID 36091357, 2022). "In contrast, removal of LepRb from at least two large populations (expressing vGat or Nos1) spanning multiple hypothalamic regions produced profound obesity and metabolic dysfunction." (PMID 29914853, 2018). "The early developmental deletion of LepRb from vGat or Nos1 neurons produced dramatic obesity, but deletion of LepRb from Pomc, Agrp, Ghrh, or Htr2c neurons minimally altered energy balance." (PMID 29914853, 2018). "Genetic variants in the NOS1 and EDN1 genes appear to account for important components of the variance in endothelial function, particularly when concurrent risk factors such as obesity exist." (PMID 24063765, 2013). "Recently, it has been shown that knockout of leptin receptor in Nos1-positive neurons produces obesity similar to ob/ob mice." (PMID 24251118, 2013). "It has been shown recently that knockout of leptin receptor in Nos1-positive neurons produces obesity similar to ob/ob mice, which indicates that these neurons are the major sites of leptin signaling." (PMID 24251118, 2013).
Sepsis (19 papers, 2007 to 2023). Sepsis is defined as life-threatening organ dysfunction caused by a dysregulated host response to infection. "Remarkably, the six sepsis-elevated genes in the lungs (Il10, Tnf, Ccl3, Ccl4, Ccl12, and Nos1) were more susceptible to the nuclear blockade with the NTCI than their homologs in the kidneys." (PMID 37638006, 2023). "During inflammatory conditions and especially during sepsis, NOS1 exhibits an important immunoregulatory role, involving both pro-inflammatory and anti-inflammatory pathways." (PMID 25699985, 2015). "Supplementation of the non-selective NOS inhibitor l-NAME in an experimental hyperdynamic sepsis model in ewes lead to a normalized renal blood flow, indicating an important contribution of the local NOS1 and NOS3 derived NO production in the hypotension." (PMID 25699985, 2015). "During inflammation and sepsis, this NOS1 and NOS3-mediated NO production is reduced, reducing blood flow to the individual organs, thereby compromising its function." (PMID 25699985, 2015). "Furthermore, the role of neuronal NOS (or NOS1) seems to contribute to the hyporesponsivity of contractile adrenergic agonists in sepsis." (PMID 27445832, 2016). "Therefore, it is suggested that the upregulation of NOS2 during sepsis may compensate for the downregulation of NOS1 and NOS3 with respect to organ perfusion." (PMID 25699985, 2015). "Remarkably, NOS1 stabilizes NOS2 activity and is important for sepsis survival and bacterial clearance." (PMID 30679708, 2019). "Indeed, experimental evidence indicates that inhibition of NOS1 and NOS3 activity during sepsis increases hepatic and splanchnic damage." (PMID 25699985, 2015).
Cognitive impairment (18 papers, 2009 to 2025). Abnormal cognition is characterized by deficits in thinking, reasoning, or remembering. "In favor of this hypothesis, mice deficient in Nos1, which encodes the neuronal NO synthase (nNOS) that converts arginine to NO, display cognitive impairments, aggressivity and hyperactivity as well as additional behavioral abnormalities." (PMID 26215737, 2015). "A total of 763 individuals (see Section 2.1.6 on “Cognitive Disorders” regarding NOS1, NOS2, andNOS3) were examined." (PMID 32111088, 2020).
migraine (18 papers, 2015 to 2025). "However, the association of the primary headache with SNVs of the NOS1 gene was studied, but with other SNVs and in patients with migraines." (PMID 36292708, 2022). "The NOS1 gene encodes nitric oxide synthase (NOS), which mediates NO production – a significant factor in migraine pathogenesis." (PMID 40391079, 2025). "Additionally, methylenetetrahydrofolate reductase (MTHFR), estrogen receptor 1 (ESR1), and nitric oxide synthase 1 (NOS1), along with their methylation patterns, are considered important genes involved in migraine pathogenesis." (PMID 40391079, 2025). "However, the prognostic role of NOS1, NOS2, NOS3 genes in the development of the common AH + TTH phenotype has not been studied in comparison with the second most common phenotype (AH + migraine)." (PMID 33809023, 2021).
asthma (17 papers, 2007 to 2024). "Several studies showed that NOS1 gene polymorphism was associated with asthma, OTP played an essential role in the specification of neuronal cell lineages in the developing hypothalamus and NANOS1 was required for maintaining oocyte production." (PMID 29416711, 2018). "In particular, seven gene targets (HMGCR, ADORA1, IL6R, CD86, BCR, PIK3CD, and NOS1) are prioritized for asthma drug repurposing." (PMID 35052792, 2022). "We similarly observed an association with asthma following severe RSV bronchiolitis and rare nonsynonymous variants in FLG and NCAM1 in European Americans, and NOS1 in African Americans." (PMID 26587832, 2015). "Additionally, our bioinformatic networking analysis also showed that CD86 and NOS1 are promising targets for asthma drug repurposing." (PMID 35052792, 2022). "Some NOS1 and NOS3 polymorphisms studied in various populations showed a positive correlation with atopy, total IgE concentration or sensitization to inhaled allergens (e.g., Dermatophagoides pteronyssinus) and a possible relationship with the risk of asthma." (PMID 34946286, 2021). "And thus, it remains possible that the association at NOS1 is due to an imbalance in the proportion of European admixture, rather than a true genetic association with asthma following severe RSV." (PMID 26587832, 2015). "Further validation of these variants through Sanger sequencing in asthma cases confirmed the presence of the minor allele in 6 carriers of rs1800888 in ADRB2 (European Americans), one carrier of rs35576001 in NCAM1 (a European American), and one carrier of rs76090928 in NOS1 (an African American)." (PMID 26587832, 2015). "NOS1-KO mice recruit fewer eosinophils (~ 70% of wild-type) and produce less NO (~ 10% of wild-type) in a mouse model of OVA-induced asthma, and upregulation of NOS2 is abolished." (PMID 29792217, 2018). "SNPs (N = 121) belonging to NOS1, NOS2 and NOS3 genes were genotyped in 1277 adults from the French Epidemiological study on the Genetics and Environment of Asthma (EGEA)." (PMID 22590587, 2012).
endothelial dysfunction (17 papers, 2012 to 2024). In vascular diseases, endothelial dysfunction is a systemic pathological state of the endothelium (the inner lining of blood vessels) and can be broadly defined as an imbalance between vasodilating and vasoconstricting substances produced by (or acting on) the endothelium. "Nitric oxide synthase (NOS) has been proposed to contribute to endothelial dysfunction in HFpEF, and NOS1 inhibition was recently associated with recovery of diastolic dysfunction in a murine model resembling HFpEF." (PMID 37488529, 2023). "The endothelial dysfunction is linked to an increase in •NO production by NOS1." (PMID 35633883, 2022). "An increase in NOS1 expression could led to endothelial dysfunction and is associated with an increase in O2•- production." (PMID 35633883, 2022).
myocardial infarction (17 papers, 2009 to 2025). Gross necrosis of the myocardium, as a result of interruption of the blood supply to the area, as in coronary thrombosis. "Cytosolic nNOS translocates to caveolae post myocardial infarction and this is facilitated by its own shuttle adaptor protein, NOS1-AP/CAPON." (PMID 27590099, 2016). "Aerobic exercise inhibits cardiac sympathetic nerve sprouting, restores β3-AR/β1-AR balance and increases β3-AR expression through the activation of NOS2 and NOS1 after myocardial infarction." (PMID 24842290, 2014). "In a complementary experiment, after myocardial infarction, in mice with genetic deletion of NOS1 (which is increased in PP2A-TG) pronounced cardiomyocyte hypertrophy and left ventricular dilation was noted: this suggested to the authors a protective role of NOS1." (PMID 35563079, 2022).
neuroblastoma (17 papers, 2011 to 2025). Neuroblastoma (NB) is the most common solid, extracranial childhood tumor. "Regarding the other two NOS isoforms, NOS3 expression strongly correlates with iNOS presence in breast carcinoma and NOS1 has been detected in some oligodendrogliomas and neuroblastomas cell lines." (PMID 24605112, 2014). "On the other hand, miR-152 targeting DNMT1 induces DNA demethylation in distinct genomic regions of nitric oxide synthase 1 (NOS1), increasing its expression in neuroblastoma cells." (PMID 37345170, 2023). "To examine whether NOS1 expression is required for the action of ARL-17477, we generated NOS1-knockout cell lines from U251-MG neuroblastoma using the CRISPR/Cas9 system." (PMID 37402770, 2023).
epilepsy (16 papers, 2015 to 2025). A brain disorder characterized by episodes of abnormally increased neuronal discharge resulting in transient episodes of sensory or motor neurological dysfunction, or psychic dysfunction. "The susceptibility to pilocarpine-induced SE in Nos1−/− mice was likely caused by over-activated excitatory neurons through epilepsy-like hyperexcitatory afferent circuits in the hippocampal DG." (PMID 39653809, 2025). "To probe into whether hippocampal nNOS deficiency plays a crucial role in the pathology of epilepsy, we treated Nos1 knockout (nNOS KO, Nos1−/−) mice and their wild type (WT) littermates with different dosages of pilocarpine." (PMID 39653809, 2025). "Nos1 deletion led to excessive epilepsy-like excitatory input circuit formation and hyperexcitation of DGCs." (PMID 39653809, 2025).
glioma (15 papers, 2010 to 2024). A benign or malignant brain and spinal cord tumor that arises from glial cells (astrocytes, oligodendrocytes, ependymal cells). "Single nucleotide polymorphisms in SOD2, SOD3, GPX1, and NOS1 were found to significantly increase the risk of glioma development in a Chinese population." (PMID 28108734, 2017). "In contrast, we observed a decreased glioma risk associated with the NOS1 rs2682826 variant (adjusted OR = 0.61; 95% CI = 0.45-0.82; P-trend = 0.017)." (PMID 23259684, 2012). "Using single-locus analysis, we identified four SNPs (SOD2 V16A, SOD3 T58A, GPX1 -46 C/T, and NOS1 3’-UTR) that were significantly associated with the risk of glioma development." (PMID 23259684, 2012). "Four SNPs (SOD2 V16A, SOD3 T58A, GPX1 -46 C/T, and NOS1 3’-UTR) demonstrated a significant association with glioma risk, as determined by the dominant model (variant-containing genotypes versus common homozygote)." (PMID 23259684, 2012). "We examined 16 single nucleotide polymorphisms (SNPs) of 9 antioxidant genes (GPX1, CAT, PON1, NQO1, SOD2/MnSOD, SOD3, and NOS1*2*3) in 384 glioma and 384 control cases in a Chinese hospital-based case–control study." (PMID 23259684, 2012). "Nos2 was clearly overexpressed in the xenografted glioma cells when compared to Nos1 and Nos3." (PMID 25768009, 2015). "To further investigate the functions of PBX3 in glioma, we performed GSEA using TCGA data, GSEA showed that regulation of NOS1 pathway, CK1 pathway, HDAC pathway, Phosphatidylinositol system, Neurotransmitter receptor complex were differentially concentrated in PBX3 high expression phenotype." (PMID 38324550, 2024). "When we analyzed zebrafish nos expression in whole embryos injected with the glioma cells, we did not detect any significant increase in zebrafish nos1 and nos2b isoforms but saw an increase of nos2a levels, suggesting an effect of tumor-produced NO on zebrafish cells." (PMID 25768009, 2015).
Insulin resistance (14 papers, 2010 to 2024). Increased resistance towards insulin, that is, diminished effectiveness of insulin in reducing blood glucose levels. "Lastly, the NOS family consists of three members; endothelial NOS (eNOS/NOS3) reported to have an anti-obesogenic effect, the inducible NOS (iNOS/NOS2) that promotes insulin resistance, and the neuronal NOS (nNOS/NOS1) that appears to act as appetite regulator." (PMID 33924357, 2021).
muscular dystrophy (14 papers, 2007 to 2022). Muscular dystrophy (MD) refers to a group of more than 30 genetic diseases characterized by progressive weakness and degeneration of the skeletal muscles that control movement. "The mRNA of Nos1, a regulator of myogenic stem cells activation and differentiation frequently affected in muscular dystrophy, was down-regulated primarily in vastus (3 fold)." (PMID 23300487, 2013).
memory impairment (13 papers, 2006 to 2025). "Another SNP rs6490121 of NOS1 was also found to be associated with working memory impairment in schizophrenic patients, and the working memory impairment of risk allele carriers was declining." (PMID 33424660, 2020).
Duchenne muscular dystrophy (12 papers, 2009 to 2024). Duchenne muscular dystrophy (DMD) is a neuromuscular disease characterized by rapidly progressive muscle weakness and wasting due to degeneration of skeletal, smooth and cardiac muscle. "In contrast, patients with Duchenne muscular dystrophy (DMD), who lack dystrophin and NOS1 and, at least in the skeletal muscle, have raised miR-31 expression, do not have increase susceptibility to AF in the absence of left ventricular (LV) dysfunction." (PMID 38270932, 2024).
osteosarcoma (12 papers, 2011 to 2025). A usually aggressive malignant bone-forming mesenchymal neoplasm, predominantly affecting adolescents and young adults. "Our results showed for the first time that activin A promoted the osteoblastic differentiation of human osteosarcoma cells, Saos2 cells and NOS1 cells." (PMID 34948289, 2021). "In this study, the activation of Src-Stat3 signaling was observed among all tested human osteosarcoma cell lines, except NOS-1 cells that highly express AMBN." (PMID 28054649, 2017). "In this study, we used human osteosarcoma cells, Saos2 cells and NOS1 cells, as preosteoblasts." (PMID 34948289, 2021). "We confirmed the reproducibility of our results using another osteosarcoma cell line (NOS-1)." (PMID 33008481, 2020). "In each graph, two horizontal lines indicating the IC50 for the two cell lines, osteosarcoma HOS and NOS-1, are inserted." (PMID 38332155, 2024). "Real-time PCR was performed to examine the gene expression of EGR1 in osteoblast and osteosarcoma cell lines including NHOst, 143B, Saos-2, HOS, MG63, and NOS-1." (PMID 21283769, 2011).